EMILIN1 (elastin microfibril interfacer 1)
Diseases named in the same sentence as EMILIN1 in open-access papers (continued):
Sharing a sentence is not in itself a finding about the gene and the disease.
melanoma (3 papers, 2021 to 2025). A malignant, usually aggressive tumor composed of atypical, neoplastic melanocytes. "Noteworthy, EMILIN-1 overexpression led to reduced primary tumor and lymph node metastasis in B16-F1 mouse melanoma xenograft models." (PMID 34299025, 2021). "Our work is the first one reporting EMILIN-1 in secreted EVs, due to the relevance of circulating EVs as biomarkers in melanoma patients including nucleic acids and proteins, it would be interesting to analyze EMILIN-1 in circulating EVs." (PMID 34299025, 2021). "We propose a novel and not previously defined intrinsic tumor-suppressive activity of EMILIN-1 in melanoma cells that is abolished by its proteolysis and secretion in sEVs favoring tumor progression and metastatic behavior." (PMID 34299025, 2021). "Since EMILIN-1 has been already reported to have tumor suppressive like functions, we postulated that melanoma cells secrete and degrade EMILIN-1 in sEVs as a novel mechanism to inactivate its suppressive signals in melanoma." (PMID 34299025, 2021). "The fact that EMILIN-1 is lost along melanoma progression, suggests its role as a tumor suppressor-like intrinsically." (PMID 34299025, 2021). "Here, we found that EMILIN-1 is proteolyzed and secreted in small EVs (sEVs) as a novel mechanism to reduce its intracellular levels favoring metastasis in mouse melanoma lymph node metastatic cells." (PMID 34299025, 2021). "Overall, our analysis suggests that the inactivation of EMILIN-1 by proteolysis and secretion in sEVs reduce its intrinsic tumor suppressive activities in melanoma favoring tumor progression and metastasis." (PMID 34299025, 2021). "Overall, our data suggest that the proteolysis of EMILIN-1 and its secretion in sEVs is a novel mechanism of EMILIN-1 inactivation favoring melanoma metastasis." (PMID 34299025, 2021). "In order to analyze the relevance of our findings, we overexpressed EMILIN-1 in B16-F1 cells and found a reduction of effective migration and cell viability, suggesting that EMILIN-1 has intrinsic tumor suppressive activities in melanoma." (PMID 34299025, 2021). "To define the intrinsic role of EMILIN-1 in melanoma cells, we performed cell viability and cell cycle assays." (PMID 34299025, 2021). "Hence, we studied the role of EMILIN-1 in melanoma cells by analyzing its influence in cell viability and cell cycle assays." (PMID 34299025, 2021). "Altogether, our data support that EMILIN-1 proteolysis and secretion in sEVs reduce its tumor- and metastatic suppressive-like properties favoring cell viability, effective migration, tumor growth, and lymph node metastasis in mouse melanoma cells." (PMID 34299025, 2021). "Defining the EMILIN-1 “degradome” in specific melanoma scenarios could be crucial to find novel inhibitors that may lead to the reactivation of its suppressive activity in vivo." (PMID 34299025, 2021). "Therefore, it is plausible that reduction of intracellular EMILIN-1 levels observed along melanoma progression could be required for efficient and independent migration, a well-known property of melanoma cells." (PMID 34299025, 2021). "Interestingly EMILIN-1 has been previously reported to be inactivated by proteolysis in other models, suggesting that secretion and proteolysis of this protein in melanoma cells could be a novel mechanism of its inactivation." (PMID 34299025, 2021). "Therefore, we postulated that EMILIN-1 secretion and degradation in sEVs might be a novel mechanism involved in EMILIN-1 inactivation melanoma progression and metastasis." (PMID 34299025, 2021). "So far, the relevance of EMILIN-1 in human melanoma is not reported, our data support a role as suppressor intrinsically as previously reported in the microenvironment." (PMID 34299025, 2021). "We observed that cells overexpressing EMILIN-1 had no directed migration, suggesting that its overexpression impairs effective migration in melanoma cells." (PMID 34299025, 2021).
aneurysm (2 papers, 2017). Bulging or ballooning in an area of an artery secondary to arterial wall weakening. "EMILIN-1 may direct proper elastic fiber orientation to fulfill the required mechanical properties of blood vessels and may play a role in the development and progression of aortic tortuosity and aneurysm, both conditions initiated by fibulin-4 deficiency." (PMID 28717224, 2017). "The other marker of ECM degradation progress, Emilin-1, showed medium negative correlation with an aneurysm diameter on the mRNA level (rs = −0.496, p < 0,015)." (PMID 29158612, 2017).
brain tumors (2 papers, 2024 to 2026). "Specifically, EMILIN-1 can exert tumor-suppressive effects by modulating cell signaling pathways of tumor cells and EMILIN-1 can also alter the immune response and promote progression of brain tumors." (PMID 41994657, 2026).
CNS Cancers (2 papers, 2020 to 2025). "In vitro models suggest low EMILIN-1 levels correlate with aggressive phenotypes, while bioinformatics analyses paradoxically link high EMILIN-1 expression to poor prognosis in low-grade gliomas." (PMID 40643467, 2025).
cutis laxa (2 papers, 2024 to 2025). Cutis laxa (CL) is an inherited or acquired connective tissue disorder characterized by wrinkled, redundant and sagging inelastic skin associated with skeletal and developmental anomalies and, in some cases, with severe systemic involvement. "Nonetheless, on December 1, 2022, biallelic loss-of-function variants in the EMILIN1 gene were reported to cause an autosomal recessive disorder characterized by cutis laxa, arterial tortuosity, aneurysm formation, and bone fragility in six individuals." (PMID 40062121, 2025). "Lethal Arteriopathy Syndrome due to Fibulin-4 Deficiency and EMILIN-1 Related Connective Tissue Disease are closely related in terms of genetic aetiology and perhaps should be reclassified as Cutis Laxa." (PMID 39480826, 2024). "Importantly, at that time, biallelic loss-of-function variants in EMILIN1 had already been shown to cause an autosomal recessive disorder characterized by cutis laxa, arterial tortuosity, aneurysm formation, and bone fragility." (PMID 40062121, 2025).
head and neck squamous cell carcinoma (2 papers, 2025). A squamous cell carcinoma that arises from any of the following anatomic sites: lip and oral cavity, nasal cavity, paranasal sinuses, pharynx, larynx, and salivary glands. "More consistent evidence supports EMILIN-1’s protective role in head and neck squamous cell carcinoma (HNSCC), where reduced expression correlates with second primary malignancies and poor prognosis in HPV-associated cases." (PMID 40643467, 2025). "It was identified from head and neck squamous cell carcinoma (HNSCC) tissues that down-regulated EMILIN-1." (PMID 39892781, 2025). "Recent studies have shown that EMILIN-1 exerts its tumor suppressor function in head and neck squamous cell carcinomas by downregulating the cell cycle and Aurora kinase signaling pathways." (PMID 40643467, 2025).
lung carcinoma (2 papers, 2021 to 2023). "Reduced EMILIN-1 production in some tumor types is associated with higher proliferation of tumor cells in breast and lung cancer." (PMID 37508851, 2023).
lymphedema (2 papers, 2021 to 2025). Excess fluid collection in tissues, causing swelling. "Therapeutic intervention with sivelestat, a selective neutrophil elastase inhibitor, effectively preserved EMILIN-1 integrity and restored lymphatic function, demonstrating a significant reduction in lymphedema." (PMID 40643467, 2025). "The local administration of Sivelestat, an inhibitor of neutrophil elastase prevents EMILIN-1 degradation and reduces lymphoedema, restoring a normal lymphatic functionality in a mouse lymphoedema model." (PMID 34299025, 2021). "The clinical relevance of these findings was further strengthened by the detection of characteristic elastase-cleaved EMILIN-1 fragments in human secondary lymphedema specimens, providing compelling evidence for neutrophil elastase inhibition as a viable treatment strategy." (PMID 40643467, 2025).
osteosarcoma (2 papers, 2022 to 2025). A usually aggressive malignant bone-forming mesenchymal neoplasm, predominantly affecting adolescents and young adults. "Despite that, some reports suggest a pro-tumorigenic role for EMILIN-1 in ovarian serous tumors and osteosarcoma." (PMID 35739492, 2022). "On the other hand, a potential tumor-promoting role has been proposed in osteosarcoma, where more elevated EMILIN-1 levels were detected compared to the less aggressive desmoids tumors, and in Ewing’s sarcoma, which also display elevated EMILIN-1 expression." (PMID 40643467, 2025).
ovarian carcinoma (2 papers, 2021 to 2025). A malignant neoplasm originating from the surface ovarian epithelium. "Proteomic analyses have identified EMILIN-1 upregulation in ovarian carcinomas, yet our findings demonstrate that the protein is frequently fragmented in ovarian cancer, leiomyosarcoma, and undifferentiated sarcoma specimens." (PMID 40643467, 2025). "Among all the proteolytic enzymes released by the tumor, neutrophil elastase (NE) was found as the main enzyme able to fully impair the regulatory function of EMILIN-1 in sarcoma and ovarian cancer." (PMID 34299025, 2021).
pulmonary stenosis (2 papers, 2025). "Here we describe a proband with short stature, tortuosity in multiple arteries, pulmonary stenosis, multiple fractures, plagiocephaly, and inverted nipples with biallelic EMILIN1 terminator variants referred to as VUS detected in his trio ES." (PMID 40062121, 2025). "There are reports of autosomal recessive EMILIN1 mutation presenting with short stature, tortuosity in multiple arteries, pulmonary stenosis, and multiple fractures." (PMID 40909027, 2025).
sarcoma (2 papers, 2021 to 2025). A usually aggressive malignant neoplasm of the soft tissue or bone. "EMILIN-1 displays strong adhesive and migratory properties for different cell types (fibroblasts, keratinocytes, trophoblast, hematopoietic, sarcoma and endothelial cells)." (PMID 40643467, 2025).
adrenocortical carcinoma (1 paper, 2022). "Mesothelioma and stomach adenocarcinoma displayed a higher expression profile for the COL1A1, COL5A1, ITGA4, and EMILIN1, in comparison to adrenocortical carcinoma and kidney renal papillary cell carcinoma." (PMID 35739492, 2022). "However, the hazard ratios remained zero with the stepwise addition of ITGA4, EMILIN1, and TSPAN9 to the Cox model in adrenocortical carcinoma, kidney renal papillary cell carcinoma, and mesothelioma." (PMID 35739492, 2022).
Aortic root aneurysm (1 paper, 2025). An abnormal localized widening (dilatation) of the aortic root. "EMILIN1 encodes for an elastic fiber-associated glycoprotein that regulates TGF-β precursor maturation and has been shown in mouse models to cause aortic root aneurysms when disrupted, likely via dysregulated signaling." (PMID 40981152, 2025). "Though human pathogenic variants have not been established, EMILIN1-deficient mouse models exhibit aortic root aneurysms and elevated TGF-β activity, suggesting a modifying role in vascular disease." (PMID 40981152, 2025).
atherosclerosis (1 paper, 2017). A disease characterized by the build-up of fatty material and calcium deposition in the arterial wall resulting in partial or complete occlusion of the arterial lumen. "Given that EMILIN1 and LOXL1 are involved in the regulation of vascular assembly and flexibility, it is possible that deamidation leading to functional impairment of these proteins could promote atherosclerosis in human patients." (PMID 28720870, 2017).
autosomal dominant cutis laxa (1 paper, 2024). Autosomal dominant cutis laxa (ADCL) is a connective tissue disorder characterized by wrinkled, redundant and sagging inelastic skin associated in some cases with internal organ involvement. "MYH11 and SYNPO2 linked to EMILIN1-related Connective Tissue Disease, AOC3 and MYH11 linked to Autosomal Dominant Cutis Laxa, MYH11 and SYNPO2 linked to Lethal Arteriopathy Syndrome due to Fibulin-4 Deficiency, while AOC3 and TAGLN linked to Renal Tubular Dysgenesis of Genetic Origin." (PMID 39480826, 2024).
autosomal dominant distal hereditary motor neuronopathy-10 (1 paper, 2025). "There is evidence that autosomal dominant distal hereditary motor neuronopathy-10 (HMND10) is caused by a heterozygous mutation in the EMILIN1 gene on chromosome 2p23." (PMID 40909027, 2025).
axonal hereditary motor sensory neuropathy (1 paper, 2025). "We report a case of axonal hereditary motor sensory neuropathy associated with a mutation in the EMILIN1 gene." (PMID 40909027, 2025).
Blindness (1 paper, 2020). Blindness is the condition of lacking visual perception defined as a profound reduction in visual perception. "In two siblings with intellectual disability, psychomotor retardation, blindness, epilepsy, movement disorder and cerebellar atrophy we identified rare homozygous variants in the genes LTBP1, EMILIN1, CACNB4, MINAR1, DHX38 and MYO15 by whole-exome sequencing." (PMID 32176688, 2020).
breast tumors (1 paper, 2025). "Recent integrated single-cell RNA sequencing and spatial transcriptomic analyses of breast tumors revealed EMILIN-1 as a top differentially expressed gene in TGF-β-rich zones associated with CD8+ T-cell infiltration." (PMID 40643467, 2025).
carcinomas of the bladder (1 paper, 2024). "A substantial decrease of EMILIN-1 expression was observed in carcinomas of the bladder, lung, ovary, rectum and uterus respect to the normal tissues, suggesting that the EMILIN-1 tumor-suppressive function may be lost in a broad spectrum of cancers." (PMID 38941035, 2024).
colorectal cancer (1 paper, 2024). A primary or metastatic malignant neoplasm that affects the colon or rectum. "Loss of EMILIN-1 has previously been linked to neoplastic progression in skin and colorectal cancer models." (PMID 38941035, 2024).
dentin caries (1 paper, 2020). "In dentin caries, a non-significant to weak decrease of EMILIN-1 and -2 was detected in the odontoblasts, in their processes, and in the ECM of pre-dentin as well as of the dental pulp." (PMID 32948785, 2020).
diffuse astrocytoma (1 paper, 2020). A low-grade (WHO grade II) astrocytic neoplasm. "We found that EMILIN1 and EMILIN2 were overexpressed in diffuse astrocytoma compared to normal brain tissue." (PMID 32175193, 2020).
distal motor neuropathy (1 paper, 2025). "There is a report of a family with distal motor neuropathy associated with the EMILIN1 mutation." (PMID 40909027, 2025).
emphysema (1 paper, 2021). "In our study, COL6A1 and EMILIN1, two genes involved in ECM organization, were also enriched in emphysema, and therefore their function in emphysema and COPD merits further research." (PMID 33535173, 2021).
Ewing sarcoma (1 paper, 2025). A small round cell tumor that lacks morphologic, immunohistochemical, and electron microscopic evidence of neuroectodermal differentiation. "In Ewing’s sarcoma, concomitant MMP9 upregulation suggests that proteolytic regulation may determine net EMILIN-1 bioavailability." (PMID 40643467, 2025).
hereditary distal motor neuronopathy (1 paper, 2025). "Sensory motor polyneuropathy and hereditary distal motor neuronopathy can be rare manifestations of the EMILIN1 mutation." (PMID 40909027, 2025).
Infertility (1 paper, 2025). "Also, menstrual blood serum was characterized as a less invasive source of infertility biomarkers, where EMILIN1, TRIP6, LAMB1, LAMC1, NID1, APOB, APOA4 were detected as the main differences in uIF patients as compared to healthy controls." (PMID 40861859, 2025).
leiomyosarcoma (1 paper, 2025). An uncommon, aggressive malignant smooth muscle neoplasm, usually occurring in post-menopausal women. "Despite the up-regulation of EMILIN1 expression, extensive fragmentation has been observed in ovarian tumors, leiomyosarcomas, and undifferentiated soft tissue sarcomas, suggesting that the protein may not be functional." (PMID 39892781, 2025).
low grade glioma (1 paper, 2022). A grade I or grade II glioma arising from the central nervous system. "However, EMILIN1 overexpression was detected in serous ovarian carcinoma, soft tissue osteosarcoma, and low-grade glioma (LGG) which are malignant tumors with high recurrence rates." (PMID 35739492, 2022).
mammary adenocarcinomas (1 paper, 2024). "To elucidate the role of EMILIN1 in BC, we analyzed the phenotype of MMTV-Δ16HER2 transgenic mice, developing spontaneous multifocal mammary adenocarcinomas, crossed with EMILIN1 knock-out (KO) animals." (PMID 38184660, 2024).
mesenchymal tumors (1 paper, 2025). "This is especially apparent in mesenchymal tumors, where EMILIN-1 levels are heterogeneous and show limited predictive value for clinical outcomes." (PMID 40643467, 2025). "The relationship between EMILIN-1 expression and clinical outcomes in mesenchymal tumors remains context-dependent." (PMID 40643467, 2025).
myocardial infarction (1 paper, 2022). Gross necrosis of the myocardium, as a result of interruption of the blood supply to the area, as in coronary thrombosis. "These genes were previously reported to protect the failing heart from adverse remodeling and dysfunction (Thbs1 and Sparc) or involved in collagen maturation and matrix production in reparative post-myocardial infarction (MI) (Emilin1 and Postn)." (PMID 35203431, 2022).
stomach adenocarcinoma (1 paper, 2022). "Despite that, adding TSPAN9 to the COL1A1, COL5A1, ITGA4, and EMILIN1 Cox model further increased the hazard ratio to 36.813 for CAF infiltration in stomach adenocarcinoma samples." (PMID 35739492, 2022). "The increase in the poor prognostic impact of CAFs in stomach adenocarcinoma with the addition of EMILIN1 as a covariate to the Cox model was surprising since EMILIN-1 is known as a tumor suppressor that exerts anti-proliferative action via integrin α4β1 in cell and in vivo models." (PMID 35739492, 2022). "This was in parallel to the increase in the poor prognostic impact of CAF infiltration by stage in stomach adenocarcinoma, suggesting a stage and CAF dependent role for ITGA4, EMILIN1, and TSPAN9." (PMID 35739492, 2022). "With further analysis, we revealed COL1A1, COL5A1, ITGA4, EMILIN1, and TSPAN9 as a poor prognostic gene signature for CAF infiltration, with high specificity to stomach adenocarcinoma." (PMID 35739492, 2022). "Strikingly, the correlation of EMILIN1 and TSPAN9 with CAF infiltration was quite strong in stomach adenocarcinoma compared to a poorer correlation in the other three cancers." (PMID 35739492, 2022). "All this data suggested COL1A1, COL5A1, ITGA4, EMILIN1, and TSPAN9 as a poor prognostic CAF signature with high specificity to stomach adenocarcinoma." (PMID 35739492, 2022). "Based on the comparative pan-cancer analysis of these key CAF markers and a comprehensive literature search we identified COL1A1, COL5A1, ITGA4, EMILIN1, and TSPAN9 as the signature genes, which potentiated the poor prognostic impact of CAF infiltration specifically in stomach adenocarcinoma." (PMID 35739492, 2022). "Our investigation of TCGA stomach adenocarcinoma data does not suggest either a poor or a good prognostic role for EMILIN1 or TSPAN9 per se." (PMID 35739492, 2022). "The KM-survival analysis did not indicate a prognostic role for ITGA4, EMILIN1, or TSPAN9 in stomach adenocarcinoma per se." (PMID 35739492, 2022).
thrombosis (1 paper, 2013). "We identified EMILIN2, with a high homology to EMILIN1, in the QTL on chromosome 17, in the Hmtb8 locus and found a thrombosis phenotype." (PMID 24147020, 2013).